MTM1 (myotubularin 1)
Diseases named in the same sentence as MTM1 in open-access papers (continued):
Sharing a sentence is not in itself a finding about the gene and the disease.
myopathy (28 papers, 2010 to 2025). A disease of the muscle in which the muscle fibers do not function properly. "The knock-in (MTM1-KI) mouse carried a point mutation at R69C and exhibit mild progression of the myopathy with median life span of 66 weeks and we analyzed tissues taken at 5, 10, and 20 weeks of age." (PMID 33732165, 2021). "This study confirms the epistasis between Mtm1 and Dnm2 and the ‘cross-therapy' rationale that targeting another myopathy gene (DNM2) than the one mutated in the disease (MTM1) can efficiently re-balance muscle function." (PMID 28589938, 2017). "By combining next generation sequencing (NGS) and CGH array approaches, we have investigated the role of MTM1 variants in a large cohort of undiagnosed patients with a wide spectrum of myopathies." (PMID 27017278, 2016). "The number of MTM1 mutations resulting in similar severe and progressive clinical myopathy and histopathological changes are likely to increase as canine myopathies are further characterized." (PMID 25664165, 2015). "Mutations in the MTM1 gene, while primarily causing a myopathy in males, may exert subclinical effects on smooth muscle and connective tissue integrity in female carriers." (PMID 41328088, 2025). "A.R.F. has been a member of an independent data monitoring committee for a different clinical trial for MTM1-related myopathy and DNM2-related myopathy (the trial was terminated early)." (PMID 40979471, 2025). "Taken together, these findings suggest that the targeting of PI3KC2β represents a therapy specifically for MTM1 myopathy." (PMID 36943412, 2023). "Of the DNM2‐CNM patients, 61% had family members with a diagnosed myopathy; in MTM1 and RYR1 patients this was the case in 50% and 44%, respectively." (PMID 34463354, 2021). "Earlier studies have showing the rescue of MTM1 myopathy by MTMR2 overexpression, emphasize the importance of maintaining the phosphoinositides equilibrium and highlight a potential compensatory mechanism amongst members of this pathway." (PMID 31680794, 2019). "It was recently shown that MTMR2 can rescue MTM1-myopathy, with the short isoform being more effective." (PMID 31680794, 2019). "More interestingly, we also identified two girls with a sporadic myopathy and an unremarkable family history for possible MTM1-related conditions or other neuromuscular disorders." (PMID 27017278, 2016). "Considering the broad range of phenotypes caused by MTM1 mutations, the presence of necklace fibers at muscle biopsy is a hallmark of this specific disease as well as of a DNM2 related myopathy." (PMID 27017278, 2016). "In the disease benchmark data set, myopathy contains 41 relevant genes so we built the disease model using the other 40 genes and left MTM1 out with 99 random candidate genes for validation." (PMID 20074336, 2010). "Mtm1-KI C375S mice present a decreased survival and a progressive myopathy." (PMID 41086017, 2025). "Congenital myopathies with mislocalized nuclei include CNMs and are genetically heterogeneous diseases caused by mutations in at least seven genes (MTM1, DNM2, BIN1, RYR1, TTN, SPEG and ZAK), with MTM1, DNM2, BIN1 and RYR1 being the most frequently associated." (PMID 41459639, 2025). "While MTM1 is ubiquitously expressed, specific inactivation of its enzymatic activity leads to a progressive myopathy with histological hallmarks similar to XLMTM and to the full MTM1 protein loss in the Mtm1–/y mouse, supporting the loss of the phosphatase activity is the main cause of XLMTM." (PMID 41086017, 2025). "We have observed mixed results with this outcome measure in other zebrafish myopathy models, where we have successfully identified chemicals that rescue the swimming defect in mtm1 mutant zebrafish, meanwhile we found no positive hits in neb deficient zebrafish which show complete paralysis." (PMID 32223895, 2020).
myopathy (continued). "Based on previous studies and on our results, we favor the hypothesis that the MTM1 phosphatase activity is crucial for the onset of the disease but less important for its maintenance in later stages of the myopathy." (PMID 23071445, 2012). "The first example was taken from the prioritization of MTM1, a gene relevant to myopathy disease." (PMID 20074336, 2010). "Although a proven canine MTM1 null mutation has not yet been reported, it is worth noting that both the Labrador retrievers and Rottweilers exhibited similar severe clinical phenotypes, with onset of a generalized, progressive, and fatal myopathy in the second to third month of life." (PMID 25664165, 2015). "Of note, comparison of RNAseq data to age/sex matched TA muscle from another mouse with severe myopathy, a model of recessive RYR1 related myopathy, shows completely different transcriptomic signatures, supporting the specificity of PKC hyperactivation in Mtm1 KO muscle." (PMID 35844027, 2022). "This is in contrast to what has been reported for the Mtm1-null mice which although they reproduced the main histological signs of XLMTM, remain clinically asymptomatic during the first 3 weeks of life and only later developed a progressive myopathy." (PMID 24381816, 2013). "Indeed, it was shown that the disruption of the PIK3C2B kinase resulted in a complete prevention of the myopathy phenotypes in a Mtm1 disease mouse model, and inhibition of the PIK3C2B kinase activity after appearance of myopathy symptoms promoted a striking rescue in the zebrafish model." (PMID 28294977, 2017). "In conclusion, not all MTM1 mutants responsible for myopathy lack the phosphatase activity." (PMID 23071445, 2012).
genetic disorder (5 papers, 2022 to 2026). "To determine if the novel epigenomic alterations identified in Mtm1 KO mice are relevant to human XLMTM, we applied to XLMTM patient samples an established analytical pipeline for characterizing DNA methylation changes in rare genetic disorders of epigenetic regulation." (PMID 35844027, 2022).
tumor (4 papers, 2017 to 2025). "Strikingly, MTM1—a core triaptosis-associated gene—showed elevated expression in malignant cells from tumor tissues." (PMID 41304936, 2025). "Circ_FURIN silencing protected against TTR-induced dysfunction by the miR-423-5p/MTM1 pathway in human ovarian granulosa-like tumor cells." (PMID 35177076, 2022). "The integration of single-cell transcriptomics further uncovered MTM1 upregulation in malignant hepatocytes, suggesting that triaptosis activation could selectively target tumor cells while sparing normal tissues—a critical advantage for therapeutic development." (PMID 41304936, 2025). "This synergistic hyperactivation of proliferative and inflammatory pathways aligns with clinically aggressive tumor phenotypes, suggesting that MTM1-enriched malignant cells may represent a therapeutically targetable subpopulation primed for triaptosis induction." (PMID 41304936, 2025).
neuromuscular disease (3 papers, 2015 to 2023). "MTM1 is part of a large family of proteins mutated in different neuromuscular diseases." (PMID 36943412, 2023). "Within this cohort, mutations were found in eight previously known neuromuscular disease genes (CHRND, CHNRG, ECEL1, GBE1, MTM1, MYH3, NEB and RYR1) and four novel neuromuscular disease genes were identified and have been published as separate reports (GPR126, KLHL40, KLHL41 and SPEG)." (PMID 26578207, 2015). "Mutations were found in eight previously known neuromuscular disease genes (CHRND, CHNRG, ECEL1, GBE1, MTM1, MYH3, NEB and RYR1) and four novel neuromuscular disease genes (GPR126, KLHL40, KLHL41 and SPEG)." (PMID 26933539, 2015).
cancer (2 papers, 2015 to 2023). A tumor composed of atypical neoplastic, often pleomorphic cells that invade other tissues. "It would be interesting to investigate whether and how the recruitment of MTM1 and PI4KIIα to MVEs are regulated under different pathophysiological conditions such as cancer." (PMID 37898620, 2023).
peripheral nervous system disease (1 paper, 2021). "We also observed that proteins enriched in GO term of peripheral nervous system disease, including MAP4, MTM1, MYO5A and GDAP1, were significantly increased in T2DM‐MCI patients." (PMID 34528736, 2021).
peripheral neuropathies (1 paper, 2025). "The MTM1 gene codes for the protein myotubularin (MTM1) that defined a large family of proteins conserved through evolution, with several paralogs mutated in peripheral neuropathies." (PMID 41086017, 2025).
MTM1 also shares sentences with these, for which no sentence is quoted: centronuclear myopathy (33 papers); Cholestatic liver disease (2); epilepsy (2); Intellectual disability (2); intrahepatic cholestasis (2); microcephaly (2); respiratory failure (2); Amoebiasis (1); Ataxia (1); Autoimmunity (1); cataract (1); Cerebellar atrophy (1); Charcot-Marie-Tooth disease (1); congenital fibre type disproportion (1); deafness, autosomal recessive 1A (1); developmental delay (1); distal myopathy (1); Duchenne muscular dystrophy (1); dwarfism (1); dystroglycanopathy (1); facioscapulohumeral muscular dystrophy 2 (1); Hunter syndrome (1); Huntington disease (1); hypospadias (1); Idiopathic inflammatory myopathies (1); infection (1); Joubert syndrome 1 (1); Joubert syndrome 8 (1); melanoma (1); MELAS (1).
A further 19 diseases each share a sentence with MTM1 in 1 paper.